KIR2DL4 (killer cell immunoglobulin like receptor, two Ig domains and long cytoplasmic tail 4)
Diseases named in the same sentence as KIR2DL4 in open-access papers (continued):
Sharing a sentence is not in itself a finding about the gene and the disease.
COVID-19 (3 papers, 2021 to 2025). A disease caused by infection with severe acute respiratory syndrome coronavirus 2. "In our case report, the dynamics of HLA-G and expression of its receptors ILT-2, ILT4, and KIR2DL4 on peripheral immune cell subpopulations in a critical COVID-19 case to convalescence were analysed." (PMID 34938296, 2021). "The aberrant expression of CD158d for the killer cell immunoglobulin-like receptor KIR2DL4 observed in parts of the granulocyte populations in two patients has not been described in severe COVID-19 before, and the significance is yet to be explained." (PMID 35625671, 2022).
infertile (3 papers, 2015 to 2020). "In contrast, the numbers of decidual mast cells and KIR2DL4 expression was significantly reduced in infertile women long-term treated with corticosteroids for autoimmune diseases, liver transplantation, or kidney transplantation." (PMID 32023940, 2020). "Lower CD56+KIR2DL4+ (e)NK cell percentages were detected in primary infertile women compared with secondary infertile women." (PMID 25764161, 2015). "In addition, a lower number of endometrial CD56+KIR2DL4+ NK cells were found in primary infertile than in secondary infertile women." (PMID 27652273, 2016).
asthma (2 papers, 2016 to 2021). "KIR2DL4 genotypes were analyzed in 2 cohorts of children at high risk for atopic disease and asthma." (PMID 35082780, 2021).
colorectal cancer (2 papers, 2021 to 2024). A primary or metastatic malignant neoplasm that affects the colon or rectum. "(D) mIHC of GZMK+ and KIR2DL4+ NK cells in primary colorectal cancer and liver metastasis cancer." (PMID 39387546, 2024).
mastocytosis (2 papers, 2017 to 2020). A clonal myeloproliferative neoplasm characterized by the proliferation and accumulation of neoplastic mast cells in one or multiple organs or organ systems. "Some human mastocytosis (six of 15 cutaneous mastocytosis cases) expressed KIR2DL4 protein, however, whether KIR2DL4 stimulation suppresses the growth of KIT-mutated neoplastic mast cells in vitro has not been determined." (PMID 32023940, 2020). "KIR2DL4-targeted therapy might be useful, especially when a second mutation in the KIT gene is caused during avapritinib-utilized mastocytosis therapy." (PMID 32023940, 2020). "Additionally, NK cell lymphoma and neoplastic mast cells (mastocytosis) express KIR2DL4 immunohistochemically." (PMID 28445138, 2017). "The function of KIR2DL4 has been reported in human natural killer cell lymphoma and mastocytosis, but not in Langerhans cell histiocytosis (LCH)." (PMID 28445138, 2017). "In contrast, we observed that the KIR2DL4 protein expression was lacking in the human neoplastic mast cell line HMC1.2 expressing mutated KIT and deficient in FcεRI expression, and that nine of 15 cutaneous mastocytosis samples were KIR2DL4-negative." (PMID 32023940, 2020). "We previously detected KIR2DL4 protein in the cytoplasm, but not in the membrane, of the human mastocytosis cell line HMC1.2 and HMC1.2 cell growth was not affected by addition of the anti-KIR2DL4 agonistic antibody." (PMID 28445138, 2017).
Miscarriage (2 papers, 2016 to 2017). A pregnancy that ends at a stage in which the fetus is incapable of surviving on its own, defined as the spontaneous loss of a fetus before the 22th week of pregnancy. "Otherwise, none of the remaining polymorphic positions had any association with miscarriage (xdf=132 = 3.02, p = 0.9979), including woman’s genotype in polyA of the KIR2DL4 gene (p = 0.8397)." (PMID 26973020, 2016). "Multivariate analysis indicated that women’s −716 HLA-G and LILRB1 and men’s KIR2DL4 9A/10A are important in terms of the protection or susceptibility to miscarriage, respectively (p = 0.00968)." (PMID 26973020, 2016). "Moreover, a study performed by our group on the KIR, LILRB1 and HLA-G association with spontaneous miscarriage indicated that polymorphism of partners in KIR2DL4 could be associated with susceptibility to miscarriage of their women." (PMID 28523429, 2017). "Surprisingly, we observed more 9A/10A genotypes of KIR2DL4 gene carriers in the group of male partners from the miscarriage group in comparison to the men from the control group (p = 0.0288)." (PMID 26973020, 2016). "An interesting aspect of our analysis was the observation of the significantly higher frequency of 9A/10A KIR2DL4 genotype in men belonging to the miscarriage group." (PMID 26973020, 2016). "Why the genotype of man’s KIR2DL4 is important in susceptibility to miscarriage of his partner, but KIR2DL4 genotype of the woman is not, is hard to explain." (PMID 26973020, 2016).
abortion (1 paper, 2016). the ending of pregnancy by removing a fetus or embryo before it can survive outside the uterus. "In our case–control study, we tried to elucidate an association of particular genetic variants of KIR2DL4, LILRB1 and its ligand HLA-G in women as well as in their partners with susceptibility to spontaneous abortion." (PMID 26973020, 2016).
allergic reactions (1 paper, 2020). "Interference with the KIT-mediated and FcεRI-mediated signal pathways has been proposed as a potential strategy to control mast cell-mediated allergic reactions, highlighting the importance of KIR2DL4 as a target for allergic diseases." (PMID 32023940, 2020). "In other words, the agonistic antibodies against KIR2DL4 would be useful for allergy therapy, similar to the anti-IgE antibody omalizumab clinically utilized to neutralize IgE in blood, and eliminate of FcɛRI-mediated function and control mast cell-mediated allergic reactions." (PMID 32023940, 2020).
bipolar disorder (1 paper, 2022). A disorder of the brain that causes unusual shifts in mood, energy, activity levels and the ability to carry out day-to-day tasks. "In-depth analysis of the top 15 high-impact SNPs also confirmed an overlap between genotypes, with only three genes with confirmed SNPs related to neurological diseases (FRG2C for bipolar disorder, and CDC27 and KIR2DL4 for white matter microstructure measurements)." (PMID 35792828, 2022).
cervical squamous cell carcinoma (1 paper, 2024). A squamous cell carcinoma arising from the cervical epithelium. "In cervical squamous cell carcinoma (CESC), ICOS, KIR2DL4, TNFSF9, and CD86 function in immune activation and display a negative association with METTL3 expression." (PMID 39199429, 2024).
colon cancer (1 paper, 2024). "(*: p<0.05, **:p<0.01, ***:p<0.001) (C) The signature scores of GZMK+ resting NK cells (upper) and KIR2DL4+ activated NK cells (lower) in colon cancer and liver metastasis in the spatial transcriptomic sections." (PMID 39387546, 2024). "KIR2DL4+ activated NK cells were lessened in proportion with the progression of the disease from normal colon to colon cancer and liver metastasis cancer, whereas GZMK+ resting NK cells increased, suggesting that these two NK subsets were associated with metastasis." (PMID 39387546, 2024). "We next utilized mIHC to check those NK cells in the clinical tissue samples of a colon cancer patient with liver metastasis, confirming a high infiltration of GZMK+ NK cells and a low infiltration of KIR2DL4+ NK cells in live metastasis cancer." (PMID 39387546, 2024). "Interestingly, patients with colon cancer with higher infiltration of GZMK+ resting NK cells and lower infiltration of KIR2DL4+ activated NK cells exhibited shorter survival in the TCGA COAD cohort." (PMID 39387546, 2024). "ST analysis also confirmed that there was more infiltration of the KIR2DL4+ activated NK cell subset in the non-tumor area and GZMK+ resting NK cells in the tumor region, both primary colon cancer and liver metastasis." (PMID 39387546, 2024). "Further analysis of NK cell subtypes revealed a dramatic change in KIR2DL4+ activated NK cells and GZMK+ resting NK cells, whereas no other NK cell subpopulations differed in colon cancer progression." (PMID 39387546, 2024).
encephalitis (1 paper, 2024). An acute inflammatory process affecting the brain parenchyma. "One association signal was due to increased telomeric framework gene allele KIR2DL4*00103 in patients with anti-NMDAR encephalitis overall (25.4% vs. 12.5%, OR=1.98, p=6.60×10-4)." (PMID 39050850, 2024). "This, together with the fact KIR2DL4*00103 does not differ in sequence with KIR2DL4*00102 makes this pathway unlikely to be strongly involved in anti-NMDAR encephalitis." (PMID 39050850, 2024).
HCMV infection (1 paper, 2013). "Altogether, our data indicate that HCMV infection induces major changes in dNK cell receptor repertoire with increases in NKp44, NKG2C and decreases in NKp46, KIR2DL1, KIR2DL4 and ILT2 expression." (PMID 23592985, 2013).
hepatoblastoma (1 paper, 2022). Hepatoblastoma (HB) is a malignant hepatic tumor and is the most common pediatric liver cancer. "In hepatoblastoma, the interaction between HLA-C molecules and KIR2DL4 may be the mechanism by which tumor cells regulate the antitumor activity of NK cells, leading to tumor immune escape." (PMID 36507493, 2022).
influenza (1 paper, 2014). An acute viral infection of the respiratory tract, occurring in isolated cases, in epidemics, or in pandemics; it is caused by serologically different strains of viruses (influenzaviruses) designated A, B, and C, has a 3-day incubation period, and usually lasts for 3 to 10 days. "NK cell response related genes such as CD247, KIR2DL4, KIR3DL1, KIR3DL3 and KLRB1 were down-regulated only in moderate and severe patients while genes such as KIR2DL1, KIR2DS4 and KIR3DL2 were down-regulated in all three groups of influenza patients." (PMID 25365328, 2014).
leukemia (1 paper, 2020). A malignant (clonal) hematologic disorder, involving hematopoietic stem cells and characterized by the presence of primitive or atypical myeloid or lymphoid cells in the bone marrow and the blood. "In addition, agonistic antibodies and human leukocyte antigen (HLA)-G, a natural ligand for KIR2DL4, induce the secretion of leukemia inhibitory factor and serine proteases from human mast cells, which have been implicated in pregnancy establishment and cancer metastasis." (PMID 32023940, 2020).
ovarian endometriosis (1 paper, 2023). A non-neoplastic disorder characterized by the growth of endometrial tissue in the ovaries. "Specifically, the expression of KIR2DL4 was remarkably downregulated, while the expressions of PROK1, IGFBP1, RBP4, G2MB, KIR3DL1, and PRF1 were significantly upregulated in ovarian endometriosis." (PMID 37662927, 2023).
Sézary syndrome (1 paper, 2017). "KIR2DL4 inhibits the activity of NK cells and may reduce activation induced cell death in these T cells in Sézary syndrome." (PMID 29236770, 2017).
teratoma (1 paper, 2024). A non-seminomatous germ cell tumor characterized by the presence of various tissues which correspond to the different germinal layers (endoderm, mesoderm, and ectoderm). "The KIR2DL4*00103, KIR2DL5B, KIR3DL3*00302 effects were significantly increased in patients with teratoma and non-teratoma cases with a larger effect in the former group." (PMID 39050850, 2024).
tumor (40 papers, 2009 to 2025). "Due to its unique structural features, KIR2DL4 plays a crucial role in orchestrating a complex interplay between immune checkpoint signaling and cytokine responses within the tumor microenvironment." (PMID 40549069, 2025). "The integration of transcriptomic analysis with experimental validation confirms the tumor-promoting role of KIR2DL4 and enhances the translational value of the model in guiding precision immunotherapy." (PMID 40319421, 2025). "The risk model incorporated immune-related genes such as GBP2, SEMA4D, and KIR2DL4, which demonstrated distinct tumor expression profiles and strong prognostic value." (PMID 40319421, 2025). "As our understanding of the role of KIR2DL4 in the tumor immune microenvironment continues to grow, more precise and effective therapies can be developed." (PMID 40549069, 2025). "In this review, we summarized and discussed the pivotal role of KIR2DL4 in tumor immunotherapy by regulating the immune response against tumor cells." (PMID 40549069, 2025). "KIR2DL4 stands out among KIRs for its distinct capacity to interact with HLA-G, a ligand frequently overexpressed on tumor cells as a means of evading immune surveillance." (PMID 40549069, 2025). "This review provides an overview of the distinctive structural characteristics of KIR2DL4, followed by an examination of its expression within the immune microenvironment of tumor and the potential utility of targeting KIR2DL4 in cancer immunotherapy." (PMID 40549069, 2025). "Upon exposure to tumor cells, NK cells significantly decreased and slightly increased the expression of activated marker KIR2DL4 and the resting marker GZMK, respectively." (PMID 39387546, 2024). "HLA-G engagement of its cognate receptors, ILT-2, ILT-4 and KIR2DL4 expressed on immune cells, can significantly induce immunosuppression and result in tumor immune escape." (PMID 35185887, 2022). "HLA-C and KIR2DL4 was one of the more significant immune cell-tumor interactions (on NK) during single-cell transcriptomic analysis of NPC." (PMID 33671917, 2021). "While the role of KIR2DL4 in the NK cells in the tumor microenvironment remains uncharacterized, we found that, in the absence of HLA-G, KIR2DL4 forms a feedback circuit with IFN-γ to promote trastuzumab-induced ADCC in vitro." (PMID 34158475, 2021). "NK–tumor interactions included HLA-C/KIR2DL4, HLA-E/CD94 (KLD1), TIM3 (HAVCR2)/Galectin-9, CD96-PVR/Nectin1 and TIGIT-PVR/Nectin2." (PMID 33671917, 2021). "This is partially explained by the fact that HLA-G is thought to suppress the cytotoxic activity of human NK cells against HLA-G-positive tumor cells via KIR2DL4 or other receptors, such as CD85j, CD85d, CD8, and CD160." (PMID 32023940, 2020). "KIR2DL4 can interact with its ligand HLA-G, which is often overexpressed in tumor cells." (PMID 40549069, 2025). "Accumulated evidences have shown that KIR2DL4 plays an important role in tumor immune escape." (PMID 40549069, 2025). "Additionally, an array of specific NK inhibitory markers, namely KIR2DL1, KIR2DL3, and KIR2DL4, were elevated, indicative of tumor-induced NK cell suppression." (PMID 40547037, 2025). "Analysis of our previously published RNA-Seq dataset, which includes various cell types found in OC ascites and omental metastases, showed selective expression of KIR2DL1, KIR2DL4, and NCR1 in tumor-associated NK cells (TANK), and KLRK1 and NCR3 in both TANK and tumor-associated T cells (TAT)." (PMID 39563446, 2024). "We also detected the coordinated expression of KIR2DL4 and PD-1 in these tumor tissues." (PMID 34158475, 2021). "In addition, autocrine TGF-β signaling in tumor cells also promoted the expression of HLA-G, which bound to KIR2DL4 and enabled tumor cells to inhibit the activation of NK cells." (PMID 34158475, 2021). "The tumor cells in 27 of 36 LCH cases (75.0%) were immunohistochemically positive for KIR2DL4." (PMID 28445138, 2017).
tumor (continued). "According to this study, blockade of KIR2DL4/HLA-G signaling using specific antibodies or other immunomodulatory agents, might be possible to enhance the antitumor activity of immune cells and improve the efficacy of tumor immunotherapy." (PMID 40549069, 2025). "Consequently, the investigation of the targeting KIR2DL4 therapy has garnered significant attention in the realm of research, as it presents promising opportunities for the advancement of novel immunotherapeutic approaches aimed at bolstering anti-tumor immune responses." (PMID 40549069, 2025). "Consistent with previous studies, we also observed that the expression of the KIR2DL4+ activated NK cell subtype was decreased during CCLM progression, possibly reflecting the anti-tumor activity of this population." (PMID 39387546, 2024). "In human lung cancer, there are many important anti-tumor costimulatory molecules such as SIRPG and KIR2DL4 on the surface of TRM cells, which help the CTLs kill tumor cells." (PMID 34707601, 2021). "In the group of novel hub genes, low expression levels of UBE2L6, KIR2DL4, IFIT2, and CLEC4E were observed in tumor cells, while high expression levels of SRPX2 and EDN3 were found in SKCM." (PMID 34660598, 2021). "Functionally, HLA-G has comprehensive immunosuppressive properties exerted in multiple steps to weaken anti-tumor immune responses by acting on immune cells through its inhibitory receptors: ILT2(CD85j/LILRB1), ILT4(CD85d/LILRB2), and KIR2DL4(CD158d)." (PMID 32670296, 2020). "Mechanistically, this immunosuppressive function of HLA-G has been partially shown to operate by inhibiting the cellular anti-tumor immune response and tumor cell killing through its interaction with receptors ILT2, ILT4, and KIR2DL4 expressed on cytotoxic T cells and NK cells." (PMID 39469714, 2024). "Most of the studies on KIR2DL4 and BPIFB1 are tumor-oriented, and the expression of KIR2DL4 and BPIFB1 in AMI samples is down-regulated, which may be helpful for AMI research." (PMID 39417451, 2024). "The HLA-G molecule can interact with leukocyte receptors (e.g., ILT-2 [LILRB1/CD85j], ILT-4 [LILRB2/CD85d], and KIR2DL4 [CD158d]), mostly on CD8+ T and natural killer (NK) cells, inducing inhibitory cytotoxic responses, facilitating tumor cell proliferation and spread." (PMID 37569841, 2023). "Antibodies against HLA-G/KIR2DL4 combined with trastuzumab and NK cells, but not blocking antibodies alone, suppressed tumor growth in vivo, suggesting that these blocking antibodies exert a tumoricidal role at least partially by enhancing ADCC activity." (PMID 34158475, 2021). "Among receptors expressed on NK cells, inhibitory receptors (KIR2DL4; CD94) and activating receptors (ITGB2; KIR2DS5; NKG2C/E; NKp46) were identified which may work as sensors to discriminate normal cells and tumor cells." (PMID 25826780, 2015). "Correlative elaboration of key molecules including FCER1G, ZGMM, KIR2DL4, KIR3DH5, KLRC1, KLRB1, and FKBP5 among the 5 cell‐type clusters in evolutionary development trajectory of NKT for immune escalation against evasion of vital tumor cells and mutants was further illustrated by Violin plots." (PMID 37693048, 2023). "Here, by using a ccRCC cellular model, we demonstrate, for the first time, that HLA-G modifies the expression of genes related to tumor development, tumor angiogenesis, mitochondria metabolism and ion channels, in the absence of its known receptors ILT2, ILT4 or KIR2DL4." (PMID 39358558, 2024). "However, it was previously reported that a broad spectrum of tumours often up-regulates the expression of non-classical HLA class I, like HLA-G which dampens the NK-cell responses by engaging inhibitory receptors ILT-2 and KIR2DL4." (PMID 19755991, 2009).